LEP (leptin)
Diseases named in the same sentence as LEP in open-access papers (continued):
Sharing a sentence is not in itself a finding about the gene and the disease.
Insulin resistance (continued). "In line with this, our results indicated that OVX and diabetic female rats developed insulin resistance, suggested by the elevated level of leptin and reduced level of adiponectin in serum and adipose tissues." (PMID 25834745, 2015). "They adjusted for several factors like systolic blood pressure, body mass index, gender, insulin resistance, and age and used a multivariate linear regression model that showed that fasting leptin was inversely and significantly related to LVMI." (PMID 26064110, 2015). "The neuron-specific IR knockout mice (NIRKO) had hyperphagia, the increased body weight, hyperglycemia, moderate insulin resistance, and the increased levels of insulin, leptin and triglycerides." (PMID 28031898, 2015). "As part of this study, assessments of fetal adiposity and neonatal anthropometry were recorded, and longitudinal assessments of maternal and fetal insulin resistance, and leptin concentrations, were performed." (PMID 26368559, 2015). "Serum leptin, resistin, and lipocalin are increased in psoriasis patients and have a potential important role for developing insulin resistance and cardiovascular disease in psoriasis." (PMID 26339139, 2015). "The levels of glucose, insulin, and leptin and the homeostasis model assessment for insulin resistance (HOMA-IR) were also significantly elevated in the HFD-OP mice." (PMID 26592433, 2015). "The authors aimed to show the effects of the reduction mammaplasty on serum leptin levels and insulin resistance." (PMID 26550014, 2015). "Leptin and insulin resistance has recently been reported in the hypothalamus of diabetic mice, thereby opening new ways for a better understanding of insulin resistance and type 2 diabetes." (PMID 25346723, 2014). "Mice fed with the fat-enriched regimen presented abdominal obesity, increased blood glucose, elevated leptin level, glucose intolerance, and insulin resistance." (PMID 25142225, 2014). "Age; sex; laboratory test parameters; homeostasis model assessment-insulin resistance; and levels of leptin, adiponectin, and irisin were assessed." (PMID 25343462, 2014). "This relation was found to be mediated by impaired hormonal satiety signaling, i.e., increased leptin levels and insulin resistance." (PMID 25368558, 2014). "Then, in two mouse models of insulin resistance, leptin-deficiency and high-fat diet feeding, third intra-cerebro-ventricular infusions of FGF19 improved glycemic status, reduced insulin resistance and potentiated insulin signaling in the periphery." (PMID 24567901, 2014). "Plasma leptin levels which are elevated in obese individuals and which correlate positively with BMI and insulin resistance have also been related to hypertensive and diabetic retinopathy." (PMID 24696683, 2014). "High serum leptin levels and insulin resistance are contributors to the pathogenesis of hepatic steatosis." (PMID 24879081, 2014). "Increased maternal body weight results in a high level of leptin, which is a factor for fetal growth retardation and intrauterine insulin resistance." (PMID 25050345, 2014). "Leptin, an adipocytokine involved in the pathogenesis of insulin resistance necessary for developing type 2 diabetes, induces β-cell apoptosis and impaired β-cell function by promoting IL-1β production in human pancreatic islets." (PMID 25403235, 2014). "Additional tests for food intake, energy expenditure, glucose metabolism and insulin resistance, and serum leptin or lipid profiles in the offspring from prenatal PAH exposure would have been informative." (PMID 25347678, 2014). "TZDs exhibit as an AMPK activator but different from metformin, and reduced liver fat accumulation and ameliorated insulin resistance due to its effect on plasma adipocytokine (including adiponectin and leptin) and more AMPK activation." (PMID 25375187, 2014). "In the present study, increased VS processing during the anticipation of food reward was mediated by both increased insulin resistance and leptin levels." (PMID 25368558, 2014).
Insulin resistance (continued). "Leptin, TNF-α, and resistin correlating with body fat mass, has been reported to be associated with insulin resistance and atherosclerosis." (PMID 24684833, 2014). "We found an improvement in leptin levels, which was the only adipokine correlated with insulin resistance in a recent study evaluating the adipocytokine profile of obese adolescents." (PMID 27433488, 2014). "Leptin, another adipokine, enhances the secretion of several cytokines by inflammatory cells and a reduction in its activity leads to insulin resistance." (PMID 25105135, 2014). "Release of TNF-α and leptin from placenta during pregnancy is considered to be a diabetogenic factor exacerbating insulin resistance." (PMID 25202741, 2014). "The methylation frequency of CpG sites located at −51 and −31 nt relative to the transcription start site of the leptin gene dropped dramatically in obese adolescents with insulin resistance." (PMID 24795698, 2014). "The role of leptin in MS pathophysiology has also been demonstrated; it affects insulin sensitivity, and induces insulin resistance and lipid accumulation." (PMID 25548896, 2014). "To further investigate the regulatory mechanism that link hyperglycemia and insulin resistance, we investigated the levels of the major insulin-sensitizing adipokines—adiponectin and leptin —as well as insulin in plasma from STZ-induced diabetic mice." (PMID 25013896, 2014). "Our mediation model indicates that insulin resistance and leptin values operate in serial to mediate the relationship between VS activity and BMI." (PMID 25368558, 2014). "This is supported by the finding that height in childhood has been positively associated with skinfold thickness, body fat percentage, obesity, impaired glucose tolerance, leptin levels, insulin resistance, and type 2 diabetes in childhood or in adult life." (PMID 24465694, 2014). "Their serum leptin levels were very low despite their markedly elevated fat mass, and they presented with morbid obesity, hypertension, dyslipidemia, hyperinsulinemia, insulin resistance, and hypogonadism." (PMID 23579596, 2013). "On the other hand, a nutrient-sensing system has also been suggested that up-regulated leptin expression during hyperinsulinemia, hypertriglyceridemia and in states of insulin resistance." (PMID 23853618, 2013). "There was also an adverse adipokine profile in post-term children, characterized by higher leptin and lower adiponectin concentrations, consistent with a greater central fat distribution and insulin resistance." (PMID 23840881, 2013). "Decreased secretion of adiponectin and leptin from adipose tissue is involved in central obesity and insulin resistance." (PMID 23476686, 2013). "Adipokines enlisted in regulation of insulin resistance are adiponectin, leptin, resistin, visfatin, chemerin, TNF-α, IL-1, IL-6, IL-8, IL-10, plasminogen activator inhibitor 1, monocyte chemoattractant protein-1, and retinol binding protein-4." (PMID 24455420, 2013). "We also aimed to determine the relationship between acylated ghrelin, leptin and insulin resistance in the study groups." (PMID 24354802, 2013). "Eight weeks of chronic exercise not only effectively improved the leptin-AMPK-ACC signaling pathway, but also alleviated the liver and whole system lipid disorders and partially reversed leptin and insulin resistance." (PMID 24455748, 2013). "The rats are leptin resistant, obese and develop hyperlipidemia, insulin resistance and hyperglycemia in a pattern similar to T2DM." (PMID 24086387, 2013). "The mechanisms that explain the direct role of leptin in hepatic insulin resistance are not well understood." (PMID 23762871, 2013). "Significant differences in age, health behaviours including current smoking, measures of adiposity, glycemic index and load, adiponectin and leptin concentration, and insulin resistance are present among ethnic groups." (PMID 23826141, 2013).
Insulin resistance (continued). "The aim of this study was to examine the effect of atorvastatin treatment on levels of leptin, adiponectin and insulin resistance, and their correlation with clinical parameters, in patients with type II diabetes." (PMID 24255692, 2013). "Leptin is believed to play a role in insulin resistance, since its levels are abnormally high in the plasma of diabetic patients." (PMID 23762167, 2013). "In lipodystrophy, where individuals lack leptin and suffer from severe insulin resistance, leptin therapy has been shown to be effective in treating the metabolic effects of the disease." (PMID 23781317, 2013). "The OB group showed weight gain, increased adiposity, insulin resistance, increased leptin levels and genotoxicity; T3 administration in OS animals led to an increase in genotoxicity and oxidative stress when compared with the OB group." (PMID 23468891, 2013). "There was also a significant relationship between leptin and the level of insulin resistance, estimated by means of the HOMA-IR (r = 0.3611, p < 0.0009)." (PMID 23986664, 2013). "In SGA children with signs of insulin resistance, results are conflicting concerning leptin levels but elevated levels have been observed in prepubertal SGA children with catch-up growth." (PMID 23781317, 2013). "In the same sense, in obese adolescents leptin has been shown to rise independently of the levels of insulin resistance and TNF-α." (PMID 23986664, 2013). "Leptin enhances the secretion of several cytokines and a reduction in its activity leads to insulin resistance." (PMID 24634792, 2013). "Among the adipokines, leptin showed a strong correlation with body mass index, fat accumulation, and insulin resistance." (PMID 24294136, 2013). "A growing number of adipokines, such as leptin and adiponectin, has been identified and a mechanistic link to the pathogenesis of insulin resistance, metabolic syndrome and dyslipidaemia has been established." (PMID 23849457, 2013). "High levels of leptin and resistin, occurring in obese individuals, promote the development of insulin resistance, whereas adiponectin seems to prevent insulin resistance." (PMID 23825152, 2013). "Recent research reported a significant association between leptin in coronary heart disease (CHD) and insulin resistance." (PMID 24282409, 2013). "The combination of adiponectin and leptin has been reported to completely reverse insulin resistance in mice." (PMID 24312343, 2013). "Physiologic leptin replacement prevents insulin resistance in uncontrolled diabetes via a mechanism unrelated to changes in food intake or body weight." (PMID 23579596, 2013). "Abdominal fat accumulation is significant in LBW children, due to high level of serum leptin and thus increased insulin resistance which consequently leads to diabetes mellitusr." (PMID 24578834, 2013). "Adiponectin plays an important role in energy homeostasis, with involvement in regulating glucose concentrations through reductions in insulin resistance and fatty acid breakdown, whereas leptin regulates food intake and energy expenditure." (PMID 24209779, 2013). "Leptin is correlated with insulin resistance and is considered a key mediator linking insulin resistance with metabolic syndrome and NAFLD." (PMID 24454366, 2013). "Both compounds reduced insulin resistance through a decrease in fat accumulation in adipose tissues and an increase in fat oxidation and potentiation of leptin signaling in obese rats." (PMID 23662132, 2013). "Leptin is another adipokine and the reduction in its activity leads to severe insulin resistance and vascular dysfunction." (PMID 24634792, 2013). "We induced the leptin and insulin resistance in the mice with 8 weeks high-fat diet feeding, which similar to the previous report." (PMID 24312343, 2013). "In contrast, the presence of adipose tissue is vital in the prevention of hepatic insulin resistance, at least in part, via secretion of the following cytokines: leptin and adiponectin." (PMID 23762871, 2013).
Insulin resistance (continued). "Leptin treatment improves insulin resistance and hyperglycemia in a specific mouse model of type 2 diabetes MKR (transgenic overexpression of a skeletal muscle dominant-negative IGF-I receptor with a lysine-to-arginine amino acid)." (PMID 23579596, 2013). "We will rather focus on the prototypical adipokines (TNF-α, IL-6, leptin, adiponectin, and resistin) highlighting their roles in the development of insulin resistance as well as in immunity and inflammation." (PMID 24455420, 2013). "HOMA-IR, a strong indicator of the development of insulin resistance, correlated with body and adipose tissue weight, fasting glucose, insulin, C-peptide, leptin and resistin (P < 0.05)." (PMID 23783067, 2013). "Studies specifically looking at the effect of OSA on Tregs in adipose tissue, leptin levels and insulin resistance would be of clear interest, but are beyond the scope of the current study." (PMID 23936084, 2013). "Thyroid dysfunction is often associated with changes in appetite and body weight as well as a decrease in both insulin resistance and serum leptin concentration." (PMID 23468891, 2013). "Development of insulin resistance is also affected by several cytokines, including leptin and resistin." (PMID 23762167, 2013). "Secondly, high-fat maintenance throughout gestation and postnatal life resulted in a severe obese phenotype characterized by the highest body weights, leptin and insulin concentrations, and most severe insulin resistance in male offspring." (PMID 22988521, 2012). "In PCOS patients, leptin positively correlated with BMI,WHR, insulin, and insulin resistance, while ghrelin was only associated with serumtestosterone levels." (PMID 25493169, 2012). "Of various adipokines, leptin and adiponectin have been proposed to be a link between adipose tissue and insulin resistance." (PMID 23316228, 2012). "Blood Glucose, insulin, leptin, lipid content and fasting insulin resistance index (FIRI) as well as liver and muscle glycogen and lipid contents were determined." (PMID 24250458, 2012). "Although leptin initially increases insulin sensitivity, long-term exposure to high leptin levels has been reported to result in insulin resistance." (PMID 23056516, 2012). "The two types of RYR used in this study significantly improved insulin resistance and decreased serum leptin levels." (PMID 23320041, 2012). "Therefore, in pubertal children, increase in serum leptin level and decrease in adiponectin level may allow the early identification of “at-risk” individuals, providing important prognostic information in predicting insulin resistance and metabolic syndrome." (PMID 23316228, 2012). "Hyperinsulinemia and/or hyperglycemia are hallmarks of the obese state and are associated with insulin resistance, aberrant glucose metabolism, chronic inflammation, and the production of other metabolic hormones such as IGF-1, leptin, and adiponectin." (PMID 23050968, 2012). "Protein tyrosine phosphatase 1B (PTP1B), a key negative regulator of leptin and insulin signaling, is positively correlated with adiposity and contributes to insulin resistance." (PMID 22389718, 2012). "Plasma leptin levels positively correlated with TG, Lp (a), Apo-A1, glucose, BMI, insulin resistance (HOMA-IR), SBP and DBP levels and negatively with HDL-C levels in T2DM patients." (PMID 23216709, 2012). "Studies have reported that the ratio of leptin and adiponectin reflects the body's insulin resistance." (PMID 22474499, 2012). "Both leptin and resistin are correlated with insulin resistance and are considered key mediators linking insulin resistance with hepatic steatosis." (PMID 22682228, 2012). "This insulin resistance is mediated in part by placental hormones, including placental growth hormone, human placental lactogen, leptin and resistin." (PMID 22363400, 2012).
Insulin resistance (continued). "Adipose tissue is considered an endocrine organ, releasing into circulation adipokines, such as leptin and adiponectin, involved in the development of insulin resistance." (PMID 22888363, 2012). "Leptin interferes with insulin signalling and in type 2 diabetes plasma leptin levels were found to be correlated with the degree of insulin resistance; therefore, insulin resistance syndrome is accompanied by hyperleptinemia as well as hyperinsulinemia." (PMID 22701480, 2012). "TLR4 mutant mice compared to WT mice had significantly higher fasting blood glucose, serum insulin, insulin resistance, serum leptin, and serum cholesterol when they received TF diet (P < 0.05)." (PMID 21314942, 2011). "We examined associations between breast cancer recurrence and adiponectin, leptin, insulin resistance, and metabolic syndrome (MetS) in a cohort of 747 patients from 2001 to 2004." (PMID 21450081, 2011). "Adipokines, e.g. TNFα, IL-6 and leptin increase insulin resistance, and consequent hyperinsulinaemia influences breast cancer progression." (PMID 21774820, 2011). "This indicates that high fat diet in part acts centrally even before meaningful weight gain to trigger leptin and insulin resistance." (PMID 22035457, 2011). "In fact, leptin, acting as a signal for sufficient energy supply, is persistently increased in women with GDM after delivery and associated with hyperglycemia and insulin resistance." (PMID 22144985, 2011). "It was shown that at time of birth, infants born from obese women had increased adiposity, homeostasis model assessment of insulin resistance (HOMA-IR, a fasting index estimating insulin resistance), cord blood leptin and interleukin-6 (IL-6) concentrations." (PMID 22110473, 2011). "On the other hand, the administration of recombinant human vaspin improved insulin sensitivity and glucose tolerance, and reverses the expression of those genes that can promote insulin resistance such as leptin, resistin and TNF-α, in diet-induced obese mice." (PMID 21526992, 2011). "CLA isomers have been reported to reduced body weight, reduced leptin levels, increase PPAR γ and adiponectin, but the results are inconsistent because its been attributed to reverse causes at the same time, insulin resistance and inflammation." (PMID 20370890, 2010). "Apocynin administration suppressed the expression of these inflammatory agents, resulting in the reduction of circulating TNF-α, IL-6, and leptin levels that normally accompany insulin resistance." (PMID 21403905, 2010). "Retinol-binding protein 4 (RBP4), leptin and resistin are adipocyte-derived biomarkers for insulin resistance and type 2 diabetes." (PMID 20633301, 2010). "The local increase of these adipokines have been directly related to insulin resistance, increasing lypolisis and increasing leptin levels." (PMID 20370890, 2010). "With the higher dose, pregnant mice demonstrated increased insulin resistance, decreased glucose tolerance, and significantly higher fasting plasma insulin, leptin, triglyceride, and glycerol levels than F0-C mice." (PMID 20488778, 2010). "Our primary outcomes are serum concentrations of leptin, adiponectin, tumour necrosis factor-alpha, C-reactive protein and interleukin-6 as well as insulin resistance." (PMID 20550712, 2010). "We investigated the potential role of leptin components in critically ill patients, because systemic inflammation, insulin resistance, and hyperglycemia are common features of critical illness." (PMID 20871818, 2010). "Low leptin levels are present with insulin resistance, and insulin infusion can induce leptin secretion." (PMID 19589139, 2009). "Using serum samples collected at 0 and 14 weeks, serum concentrations of glucose, insulin, leptin, ketones and a homeostatic model assessment for insulin resistance (HOMA-IR) were determined." (PMID 19442301, 2009). "Resistin has been considered a marker of insulin resistance; this relationship extends to leptin and WAT weight." (PMID 19642981, 2009).